S100A9 (S100 calcium binding protein A9)
Diseases named in the same sentence as S100A9 in open-access papers (continued):
Sharing a sentence is not in itself a finding about the gene and the disease.
Acute hepatitis (1 paper, 2020). Acute hepatic injury resulting from inflammation typically accompanied by increased serum alanine transaminase activity. "Higher expression of S100A8 during acute hepatitis in both trimesters and additionally S100A12 in the third trimester, with normal expression of S100A9 suggests similar role in the PR patients as well." (PMID 32012176, 2020).
acute leukemia (1 paper, 2021). A clonal (malignant) hematopoietic disorder with an acute onset, affecting the bone marrow and the peripheral blood. "Hence, the therapeutic targeting of S100A8 and S100A9 appears to be a promising way to improve treatment efficiency in acute leukemias." (PMID 33801279, 2021). "Finally, a synthesis of the different therapeutic strategies targeting S100A8 and S100A9 and their potential in the treatment of acute leukemia is discussed." (PMID 33801279, 2021). "Altogether, these data suggest that strategy targeting S100A8 and/or S100A9 might be fruitful at different stages of development of acute leukemia." (PMID 33801279, 2021). "Hence, the therapeutic targeting of S100A8 and S100A9 appears as a promising way to improve treatment efficiency in acute leukemias." (PMID 33801279, 2021). "Similarly, there are increasing data about the pathological role S100A8 and S100A9 play in the development of hematological malignancies and in particular in acute leukemias (AL)." (PMID 33801279, 2021).
Aortic dissection (1 paper, 2024). Aortic dissection refers to a tear in the intimal layer of the aorta causing a separation between the intima and the medial layers of the aorta. "Significantly, a recent study has reported an association between S100A9 and aortic dissection." (PMID 38504474, 2024). "This suggests that pro‐inflammatory macrophages may through the secretion of S100A9 mediate vascular inflammation, contributing to the development of aortic dissection." (PMID 38504474, 2024).
Ascites (1 paper, 2023). Accumulation of fluid in the peritoneal cavity (between the layers of the peritoneum that lines the abdomen). "In univariate analysis, age, WBC count, creatinine, INR, ascites grade, platelet (PLT) count, TB, HE grade, BI, S100A8, and S100A9 were connected with 28/90-day mortality." (PMID 37469934, 2023).
atrial fibrillation (1 paper, 2021). A disorder characterized by an electrocardiographic finding of a supraventricular arrhythmia characterized by the replacement of consistent P waves by rapid oscillations or fibrillatory waves that vary in size, shape and timing and are accompanied by an irregular ventricular response. "Many members of S100 family, including S100A8 and S100A9, have been involved in EMT in multiple types of cells: S100A4 was associated with expression of Snail in human cancers and atrial fibrillation." (PMID 34099591, 2021).
autism (1 paper, 2018). Persistent deficits in social interaction and communication and interaction as well as a markedly restricted repertoire of activity and interest as well as repetitive patterns of behavior. "The independent association between S100A9 levels and Childhood Autism Rating Scale (CARS) scores confirmed and expanded previous findings on the role of immune activation in the pathogenesis of ASD." (PMID 30577568, 2018). "S100A9 is a major cytosolic protein in monocytes; the monocyte count is typically elevated in autism." (PMID 30577568, 2018).
bacterial sepsis (1 paper, 2025). "The eight differentially expressed genes (DEGs) as key diagnostic markers for bacterial sepsis: FTH1, B2M, NAMPT, KLF6, SRGN, S100A6, S100A9, and S100A8." (PMID 41303672, 2025).
bladder tumors (1 paper, 2012). "In bladder tumors, overexpression of S100A4, S100A8 or S100A11, but not S100A9 in cancer tissues is associated with stage progression, invasion, metastasis and poor survival." (PMID 22838504, 2012).
carotid atherosclerosis (1 paper, 2019). A thickening and loss of elasticity of the walls of carotid arteries that occur with formation of atherosclerotic plaques. "In human, several S100 proteins, including S100A7, S100A8, S100A9, and S100A12, are linked with the severity of coronary and carotid atherosclerosis." (PMID 30886860, 2019).
choledocholithiasis (1 paper, 2012). Presence or formation of gallstones in the common bile duct. "In the bile from the PSC patients, the S100A9 concentration increased with disease activity and was significantly greater in the PSC patients relative to the control patients with choledocholithiasis." (PMID 22253789, 2012).
chronic cystitis (1 paper, 2015). Recurrent infections of the urinary bladder. "The increased expression of antimicrobial peptides such as RegIIIγ and the calgranulins (s100a8 and s100a9) is interesting because this increased expression is not sufficient to eliminate bacterial replication during chronic cystitis." (PMID 25569799, 2015).
chronic eosinophilic leukemia (1 paper, 2020). "This study was, therefore, undertaken to determine the antitumor effects of S100A8 and S100A9 on eosinophils of chronic eosinophilic leukemia." (PMID 32903598, 2020). "In conclusion, this study demonstrates that S100A8 and S100A9 trigger apoptosis of chronic eosinophilic leukemia by induction of intrinsic apoptosis and suppression of FIP1L1-PDGFRα+-mediated proliferation." (PMID 32903598, 2020). "S100A8 and S100A9 blocked tumor progression of xenografted EoL-1 and EoL-1-IR cells in NOD-SCID mice and evoked apoptosis of eosinophils derived from hypereosinophilic syndrome as well as chronic eosinophilic leukemia." (PMID 32903598, 2020).
chronic gastritis (1 paper, 2012). Inflammation of the stomach that is chronic in nature. "In addition, S100A9 and S100A8 proteins were detected in inflammatory cells in chronic gastritis." (PMID 22838504, 2012).
chronic hepatitis (1 paper, 2018). An active inflammatory process affecting the liver for more than six months. "In the future, the correlation between serum S100A9 and the risk of HCC would be investigated in patients with HBV-related chronic hepatitis." (PMID 29615081, 2018).
coronary aneurysm (1 paper, 2024). Abnormal balloon- or sac-like dilatation in the wall of coronary vessels. "Notably, research into IVIG treatment for KD has revealed elevated levels of S100A8 and S100A9 in the serum of KD patients during the acute phase, with a subsequent decline in levels post-treatment, except in cases where patients developed coronary aneurysms." (PMID 39350793, 2024).
dermatomyositis (1 paper, 2023). Dermatomyositis (DM) is a type of idiopathic inflammatory myopathy characterized by evocative skin lesions and symmetrical proximal muscle weakness. "Enriched genes including S100A12, MPO (myeloperoxidase), S100A8, CXCL10, S100A9, CD244, CD244,and TLR7 have been linked to dermatomyositis." (PMID 38137330, 2023).
diabetic cardiomyopathy (1 paper, 2025). Diabetic cardiomyopathy is a disorder of the heart muscle in people with diabetes. "In the present study, we identified S100A9 as a critical mediator in the pathogenesis of diabetic cardiomyopathy (DCM)." (PMID 40384874, 2025). "The intersection of eight publicly available GEO datasets of diabetic cardiomyopathy by transcriptomics analysis revealed S100A9 is the unique common up-regulated gene." (PMID 40384874, 2025). "To thoroughly elucidate the role of S100A9 derived from macrophages and decrease the confounding factors induced by single intervention, we gradually evaluated the effects of S100A9 inhibitor, macrophage depletion and macrophage-specific S100A9 knockout in diabetic cardiomyopathy mice." (PMID 40384874, 2025). "Whether S100A9 from other cell sources, such as cardiac fibroblasts or adipocytes in epicardial adipose tissue, also plays a crucial role in diabetic cardiomyopathy remains unknown." (PMID 40384874, 2025). "It is also important to explore whether the S100A9 derived from cardiomyocytes themselves plays a role in diabetic cardiomyopathy." (PMID 40384874, 2025).
diarrheal disease (1 paper, 2023). The condition of having at least three loose or liquid bowel movements each day. "This study revealed that knockdown of S100A9 reduced injury due to cellular inflammatory injury suggesting that S100A9 regulates the progression of diarrheal disease." (PMID 36718447, 2023).
diarrhoea (1 paper, 2022). "Some of the DEGs in diarrhoea-susceptible sheep, enriched in GO terms and sub-network analysis, included IL-6, LOC101121216 (serum amyloid A), SIGLEC1, CHI3L1, S100A9, CD14, CD68, CD86, Ovar-DRB1, IL1RL1, LOC101103238 (CXCL5), CCL22 and IL1RN." (PMID 35576023, 2022).
diffuse large B-cell lymphoma (1 paper, 2021). "A tight correlation between S100A9 and TNFSF13B was also significant in the diffuse large B cell lymphoma (DLBC) samples, indicating that S100A9 might promote TNFSF13B expression in B cell-derived cells." (PMID 34150664, 2021).
duodenal ulcer (1 paper, 2023). An ulcer in the duodenal wall. "To identify the source of elevated the levels of S100A8 and S100A9 in children with duodenal ulcer, here, we analyzed the signaling pathways generated by S100A8 and S100A9, we found that IL-17 signaling pathway is involved in S100A8 and S100A9 production." (PMID 37450409, 2023).
enthesitis (1 paper, 2013). Inflammation at the site of insertion of ligaments, tendons, and other fibrous structures into bone. "Given that a positive S100A9 signal indicates where inflammation takes place, induction of dermal inflammation, onychia, and enthesitis of digit joints and especially of DIP joints was most obvious." (PMID 23740547, 2013).
eosinophilia (1 paper, 2020). "Eosinophil apoptosis of reactive eosinophilia is inhibited by S100A8 and S100A9 treatment." (PMID 32903598, 2020).
epidermodysplasia verruciformis (1 paper, 2018). A rare inherited genodermatosis characterized by chronic infection with human papillomavirus (HPV) leading to polymorphous cutaneous lesions and high risk of developing non melanoma skin cancer. "This expression profile was also observed in a previous study, when S100A8 and S100A9 protein expression in the skin of epidermodysplasia verruciformis (EV) patients was investigated." (PMID 30567500, 2018).
experimental autoimmune encephalomyelitis (1 paper, 2021). An autoimmune demyelinating disease of the central nervous system that is produced experimentally in animals by the injection of homogenized brain or spinal cord in Freund's adjuvant. "However, the inhibitory effect of paquinimod may be incomplete in terms of S100A9 inhibition; S100A9-knockout mice had a more severe disease than C57BL/6 controls in experimental autoimmune encephalomyelitis, but they still responded to treatment with paquinimod." (PMID 33791048, 2021).
gastritis (1 paper, 2012). Inflammation of the stomach. "In adjacent non-cancerous mucosa, S100A9 was expressed in inflammatory cells infiltrating gastritis." (PMID 22838504, 2012). "Similarly to the pattern of S100A9, S100A8 was expressed exclusively in inflammatory cells infiltrating both tumor tissues and adjacent gastritis tissues." (PMID 22838504, 2012).
Hepatic hemangioma (1 paper, 2023). A congenital vascular malformation in the liver composed of masses of blood vessels that are atypical or irregular in arrangement and size. "S100A8 and S100A9 mRNAs were checked in liver samples from 32 HBV-ACLF patients with liver transplantation, 19 patients undergoing surgery for hepatic hemangioma and 10 CHB patients with needle biopsy." (PMID 37469934, 2023). "In addition, mRNA expression levels of S100A8 and S100A9 were analyzed in liver tissue samples from 32 HBV-ACLF patients, 19 hepatic hemangioma patients (used as healthy controls), and 10 CHB patients." (PMID 37469934, 2023).
hepatitis B virus infection (1 paper, 2019). A viral infection caused by the hepatitis B virus. "We identified the S100A9 protein, which has been recently classified as a novel damage-associated molecular pattern, and has been associated with hepatitis B virus infection and bovine viral diarrhea virus (BVDV), which interacts with BVDV Npro protein to decrease virus production." (PMID 31040842, 2019).
hydronephrosis (1 paper, 2020). Collection of urine in the renal pelvis that results in dilatation of the renal pelvis and calyces. "In the rats with unilateral hydronephrosis, higher gene expression of NGAL, KIM‐1, and S100a9 was observed in the kidneys with hydronephrosis than in the healthy (left) kidneys; however, this difference was not significant." (PMID 33207081, 2020).
Hyperkeratosis (1 paper, 2020). Hyperkeratosis is a histopathological term defining a thickened stratum corneum and may be present in many different skin conditions, with many possible overlaps. "This induced acanthosis, hyperkeratosis, infiltration of S100A9+ myeloid cells and increased expression of chemokines and proinflammatory cytokines in the ears and the back skin at 5d after tamoxifen injection." (PMID 32597759, 2020). "Tamoxifen induced a skin phenotype very similar to Card14LSL-E138A/+Rosa26CreERT2/+Rag1+/+ controls, with acanthosis, hyperkeratosis, S100A9+ myeloid cell infiltration and expression of chemokines and proinflammatory cytokines at 5d following tamoxifen injection." (PMID 32597759, 2020).
Hyperoxaluria (1 paper, 2023). Increased excretion of oxalates in the urine. "Preliminary results revealed that knocking out S100A8 and S100A9 could decrease renal CaOx crystal deposition in hyperoxaluria mice (data have not been published)." (PMID 37051106, 2023).
infarction (1 paper, 2024). A localised pathological necrosis of tissue resulting from obstruction of the blood supply usually by a thrombus, an embolus, or vascular torsion. "S100A9 CKO mitigated infarction volume and white matter injury, enhanced cerebral blood flow and functional recovery, and prompted anti‐inflammation phenotype and efferocytosis after tMCAO." (PMID 39107960, 2024).
infectious diarrhea (1 paper, 2023). "However, the role of S100A9 in C. perfringens type C-induced infectious diarrhea is unclear." (PMID 36718447, 2023).
Infertility (1 paper, 2020). "Thus, we hypothesized that excessive S100A9 from aging oviduct, not oocytes, decreases reproductive function, subsequently leading to infertility." (PMID 31945120, 2020).
intestinal tumors (1 paper, 2017). "S100a9 has been reported to be crucial for induction of inflammation response and development of intestinal tumors, but the clinical application of S100a9 has not been fully elucidated." (PMID 29326691, 2017).
intrauterine growth restriction (1 paper, 2025). "We took into consideration the last 15 years, using specific keywords such as pre-eclampsia, intrauterine growth restriction, inflammation, S100A8, S100A9, and calprotectin." (PMID 41155408, 2025).
irritant contact dermatitis (1 paper, 2022). "The in vivo relevance of our novel findings could be verified by a reduced immigration of monocytes in a cutaneous granuloma model and diminished inflammation during irritant contact dermatitis in the presence of S100A8/S100A9‐tetramers." (PMID 36310133, 2022).
kidney cancer (1 paper, 2011). Primary or metastatic malignant neoplasm involving the kidney. "Considering this and the apparent mitochondrial alterations in kidney cancer we selected for further validation two mitochondrial proteins (prohibitin, PRDX3) which we found as differentially expressed in our 2D-DIGE approach, and the S100-A9 protein." (PMID 21760917, 2011).
kidney inflammation (1 paper, 2024). "In the ischemia-reperfusion-induced AKI mouse model, a specific subset of monocyte-derived macrophages marked by S100a8/S100a9 expression triggered and intensified kidney inflammation." (PMID 38770013, 2024).
kidney transplant (1 paper, 2025). A surgical procedure in which one or both kidneys from a donor are implanted into a recipient. "These calcium-binding proteins, primarily expressed in monocytes, play a crucial role in kidney transplant rejections, and high expression levels of S100A8 and S100A9 in myeloid cells during kidney transplant rejections have been linked to favorable outcomes." (PMID 41030449, 2025).
leprosy (1 paper, 2022). Leprosy is a chronic infectious disease affecting primarily the skin and peripheral nervous system. "The pathogenesis of reactions in leprosy is characterised by inflammatory episodes and the protein S100A9 may be studied extensively to find a correlation between the levels of this protein and the progression of the T1R in leprosy." (PMID 36560940, 2022).
Listeria infection (1 paper, 2019). "Together, these results demonstrate that InlC ubiquitination modulates the activation of neutrophils upon Listeria infection in an S100A9-dependent manner." (PMID 31848284, 2019).
lumbar disc degeneration (1 paper, 2021). "Inhibition of these pro‐apoptotic, pro‐degradation and pro‐inflammatory effects induced by S100A9 in NP may be a favourable therapeutic strategy to slow lumbar disc degeneration." (PMID 33734570, 2021).
macrosomia (1 paper, 2016). "In GDM subjects the peptide counts for S100A9 protein independently correlated with maternal obesity and macrosomia of the newborn infants." (PMID 31448371, 2016).
Mcc (1 paper, 2024). "S100A8 and S100A9 not only have diagnostic value in Mcc infection but also hold great significance in clarifying the pathogenic mechanism of Mcc." (PMID 39061526, 2024). "The RT-qPCR results showed that S100a8 and S100a9 were up-regulated after Mcc HN-B infection." (PMID 39061526, 2024).
MELAS (1 paper, 2022). "On the contrary, the expression of HSPB1, CRYAB and S100A9 were significantly up-regulated in MELAS patients." (PMID 36254078, 2022).
monocytic leukemia (1 paper, 2014). "Similarly, other S100A8 and S100A9 regulators, such as IL-6 and TNFα, have been identified on human monocytic leukemia cells." (PMID 24956170, 2014).
myopia (1 paper, 2023). "Among those genes, Ctag2l2, whose human ortholog, CTA1A, was one of the human myopia candidate genes and S100a9, known to be implicated in the regulation of the immune response, was previously identified to be upregulated in a guinea pig FDM model." (PMID 38136985, 2023).
necrotizing enterocolitis (1 paper, 2014). Necrotizing enterocolitis (NEC) is a devastating disease that affects mostly the intestine of premature infants. "Protein S100-A8 and Protein S100-A9 are suggested as markers for early diagnosis of necrotizing enterocolitis in neonates." (PMID 25419056, 2014).
orchitis (1 paper, 2021). Inflammation of one or both testes due to viral or bacterial infections. "In orchitis, elevated S100A9 contributes in maintaining the M2 polarization of TMs, which partly explain the immunosuppressive phenotype of TMs to bacterial stimulation." (PMID 34764959, 2021). "The elevated S100A9 in orchitis helps in maintaining the M2 polarization of TMs and attenuated the ratio of M1, which usually represent the ability of macrophages to resist bacteria." (PMID 34764959, 2021). "Finally, we validated this phenomenon by inhibiting S100A9 and PI3K pathways in UPEC-induced orchitis." (PMID 34764959, 2021).
oropharyngeal squamous cell carcinoma (1 paper, 2016). "In oropharyngeal squamous cell carcinoma, S100A12 in addition to S100A8 and S100A9 was downregulated as observed by IHC; simultaneous reduction in both S100A8 and S100A12 expression was associated with worse overall patient survival." (PMID 26883112, 2016).
oropharyngeal tumors (1 paper, 2023). "Altogether, these observations show that ΔNp63 expression and a the S100A9/THBS4 predictor define two distinct molecular and prognostic subgroups of HPV-related oropharyngeal tumors and suggest that ΔNp63 may play a role in tumor progression and response to therapy." (PMID 38022675, 2023).
pestivirus infection (1 paper, 2023). "When pestivirus infection, BVDV Npro interacted with the S100A9 to restrain IFN-I expression by decreasing the availability/activity of S100A9 in cells." (PMID 36936761, 2023).